EPRS1 (glutamyl-prolyl-tRNA synthetase 1)
Description:
Multifunctional protein which primarily functions within the aminoacyl-tRNA synthetase multienzyme complex, also known as multisynthetase complex. Within the complex it catalyzes the attachment of both L-glutamate and L-proline to their cognate tRNAs in a two-step reaction where the amino acid is first activated by ATP to form a covalent intermediate with AMP. Subsequently, the activated amino acid is transferred to the acceptor end of the cognate tRNA to form L-glutamyl-tRNA(Glu) and L-prolyl-tRNA(Pro). Upon interferon-gamma stimulation, EPRS1 undergoes phosphorylation, causing its dissociation from the aminoacyl-tRNA synthetase multienzyme complex. It is recruited to form the GAIT complex, which binds to stem loop-containing GAIT elements found in the 3'-UTR of various inflammatory mRNAs, such as ceruloplasmin. The GAIT complex inhibits the translation of these mRNAs, allowing interferon-gamma to redirect the function of EPRS1 from protein synthesis to translation inhibition in specific cell contexts. Furthermore, it can function as a downstream effector in the mTORC1 signaling pathway, by promoting the translocation of SLC27A1 from the cytoplasm to the plasma membrane where it mediates the uptake of long-chain fatty acid by adipocytes. Thereby, EPRS1 also plays a role in fat metabolism and more indirectly influences lifespan.
Synonyms: EPRS; PARS; QARS; QPRS; PIG32; EARS; GLUPRORS; HLD15
Tractability: Small molecule: a structure with a bound ligand is known. Antibody: UniProt places it where antibodies can reach, with high confidence; its Gene Ontology location is reachable by antibodies, with medium confidence. PROTAC: ubiquitination databases record sites on it; a small molecule that binds it is known.
Target class: Enzyme
Gene: Protein-coding gene on chromosome 1 (219,968,598 to 220,046,616, reverse strand). Ensembl gene ENSG00000136628.
Subcellular location: Cytoplasm, cytosol; Membrane
Subcellular location (Human Protein Atlas): Cytosol; Mid piece
Pathways (Reactome):
Developmental Biology: Transcriptional and post-translational regulation of MITF-M expression and activity
Metabolism: Selenoamino acid metabolism
Metabolism of RNA: tRNA modification in the nucleus and cytosol
Metabolism of proteins: Cytosolic tRNA aminoacylation
Gene Ontology:
Molecular function: glutamate-tRNA ligase activity; GTPase binding; identical protein binding; proline-tRNA ligase activity; protein binding; protein homodimerization activity; RNA stem-loop binding; zinc ion binding; aminoacyl-tRNA ligase activity; ATP binding; nucleotide binding
Biological process: cellular response to type II interferon; glutamyl-tRNA aminoacylation; negative regulation of translation; prolyl-tRNA aminoacylation; regulation of long-chain fatty acid import into cell; cellular response to insulin stimulus; negative regulation of formation of translation preinitiation complex; tRNA aminoacylation for protein translation; translation; tRNA aminoacylation
Cellular component: aminoacyl-tRNA synthetase multienzyme complex; cytoplasm; cytosol; GAIT complex; membrane; ribonucleoprotein complex; plasma membrane
Genetic constraint (gnomAD): Loss-of-function variants: 47 observed, 109.14 expected, observed/expected ratio (o/e) 0.43, 90% interval 0.34 to 0.55. The upper end of that interval is the gene's LOEUF score, 0.55, which puts it in group 2 of 6, group 1 being the genes least tolerant of losing a copy. Missense variants: 1,079 observed, 1,273.7 expected, observed/expected ratio (o/e) 0.85, 90% interval 0.81 to 0.89. Synonymous variants: 398 observed, 429.43 expected, observed/expected ratio (o/e) 0.93, 90% interval 0.85 to 1.01.
Homologues: Orthologues: chimpanzee EPRS1 (99% identical), macaque EPRS1 (98% identical), dog EPRS1 (92% identical), pig EPRS1 (92% identical), mouse Eprs1 (89% identical), rabbit EPRS1 (88% identical), rat Eprs1 (88% identical), guinea pig EPRS1 (86% identical), tropical clawed frog eprs1 (76% identical), zebrafish eprs1 (73% identical), Drosophila melanogaster GluProRS (57% identical), Caenorhabditis elegans ears-1 (34% identical). Paralogues in human: QARS1 (15% identical), EARS2 (8% identical).